GRIK1 (glutamate ionotropic receptor kainate type subunit 1)
Diseases named in the same sentence as GRIK1 in open-access papers:
GRIK1 is named in the same sentence as 65 diseases in open-access papers, as found by Europe PMC text mining. Sharing a sentence is not in itself a finding about the gene and the disease. The quoted sentences say what the papers report.
epilepsy (15 papers, 2016 to 2025). A brain disorder characterized by episodes of abnormally increased neuronal discharge resulting in transient episodes of sensory or motor neurological dysfunction, or psychic dysfunction. "Grik1 (glutamate ionotropic receptor kainate type subunit 1) gene polymorphism was found in hamsters, while the human ortholog is associated with epilepsy development, including juvenile absence epilepsy (JAE)." (PMID 36428502, 2022). "Focusing on moderate-impact “high-quality variants”, we also identified mutations in GASH/Sal genes that were previously reported as polymorphisms associated with epilepsy, such as Cacna1a, Cacna2d3, Grik1 and Jup." (PMID 32168507, 2020). "Indeed, Grik1 has been identified previously as an epilepsy-associated gene, and it has been described in relation to Grik1 variants with juvenile absence epilepsy and with sudden unexpected death in epilepsy." (PMID 38069190, 2023). "In population pharmacokinetic models of topiramate in Chinese children with epilepsy, GRIK1 rs2832407 was identified as a significant covariate decreasing clearance." (PMID 40394707, 2025). "After searching in DrugBank, we retrieved a total of 47 anti-epileptic drugs and 151 targets, of which identified 17 target genes (CACNA1A, CHRNA4,CHRNA7,GABRA1,GABRA2,GABRB2,GABRG2,GRIK1,GRIN1,GRIN2B,KCNQ2,KCNQ3,SCN1A,SCN2A, SCN3A,SCN8A and SCN9A) were overlapped with risk genes of epilepsy." (PMID 36006933, 2022). "Additionally, the mediumblue module (Pvalb subtypes, 173 genes), while not passing the test for associating more strongly with epilepsy than with any sample, included the genes GRIK1, GRIK2, GRIK4, GRM1, GRM7, and GRIA1, suggesting a potential involvement in glutamate receptor subunits." (PMID 33028830, 2020).
Anxiety (11 papers, 2007 to 2025). Intense feelings of nervousness, tension, or panic often arise in response to interpersonal stresses. "Ex vivo electrophysiological recordings from control and MS rats were done to understand how ELS and the associated loss of Grik1 expression affects the function of the amygdala circuits implicated in anxiety-type behaviors." (PMID 34663781, 2021). "Inactivation of Grik1 expression locally in the adult amygdala reduced ongoing GABAergic transmission and was sufficient to produce a mild anxiety-like behavioral phenotype." (PMID 34663781, 2021). "The involvement of Grik1 in hyperactivity, anxiety, and fear, three core alterations in mouse models of DS35, was assessed using a battery of behavioral tests." (PMID 31676751, 2019). "Even though the behavioral phenotype in individual tests was not highly significant, the mice with local loss of Grik1 in the amygdala displayed a mild anxiety-like phenotype consistently through all the different tests." (PMID 34663781, 2021). "Here we show that maternal separation (MS) stress early in life leads to downregulation of Grik1 mRNA expression in the LA, and further, that inactivation of Grik1 expression locally in the adult amygdala is sufficient to produce a mild anxiety-like behavioral phenotype in rodents." (PMID 34663781, 2021). "By contrast, anxiety- and fear-related behavioral deficits are independent of Grik1 triplication and they are not correlated to phenotypes of basal synaptic inhibition in the basolateral region of the amygdala (BLA)." (PMID 31676751, 2019).
schizophrenia (9 papers, 2013 to 2024). A major psychotic disorder characterized by abnormalities in the perception or expression of reality. "Increased levels of Grik1 mRNA and protein, encoding the ionotropic glutamate receptor kainate-1 (Grik1), have been specifically associated with schizophrenia." (PMID 39635132, 2024). "After resequencing 516 unrelated patients with schizophrenia, 44 protein-altering variants were identified, including 12 in the GRIK1, 5 in the GRIK2, 7 in the GRIK3, 13 in the GRIK4, and 7 in the GRIK5." (PMID 35629206, 2022). "GRIK1 polymorphisms have been investigation for their associations with different diseases including Juvenile absence epilepsy, schizophrenia, alcohol dependence, topiramate’s effects on heavy drinking, topiramate-induced side effects, and hepatitis B virus (HBV)-related hepatocellular carcinoma." (PMID 25485088, 2014). "Therefore, we sequenced the exonic regions of five kainate receptor genes (GRIK1, GRIK2, GRIK3, GRIK4, and GRIK5) to identify rare pathogenic variants in patients with schizophrenia using the ion semiconductor sequencing method." (PMID 35629206, 2022).
depression (5 papers, 2017 to 2025). "The GRIK gene family (GRIK1, GRIK2, GRIK3, GRIK4, and GRIK5) has genetic variants associated with many psychiatric illnesses including; depression, obsessive–compulsive disorder, and autism." (PMID 41327126, 2025). "The higher expression of Grik1 in women relative to that in men was also detected in patients with depression." (PMID 40699779, 2025). "A number of the selected hub genes in our study have been previously reported to be related to FMS or depression, including GRIK1&2, NGF, KCNQ2, GRIA1, TRPV4, IL1A, and GABAA receptors." (PMID 37065490, 2023). "The expression levels of GRIK1 and GRIK2 were reported to be higher in the female patients with major depressive disorder." (PMID 37065490, 2023).
alcohol dependence (4 papers, 2014 to 2025). Physical and psychological dependence on alcohol. "Variation in GRIK1 has been demonstrated to be associated with alcohol dependence whereby the C allele of the single nucleotide polymorphism (SNP) rs2832407 was significantly overrepresented in individuals with alcohol dependence." (PMID 30115121, 2018).
breast carcinoma (4 papers, 2017 to 2025). "Many studies have indicated that GRIK1 is implicated in the occurrence of liver cancer and breast cancer through its involvement in glutamate signaling." (PMID 40538623, 2025). "Another seven genes (CDH13, CDH7, CTNNA2, ERBB4, GRIK1, PCDH15, and TCF7L2) were reported as associated with the breast cancer by recent GWA studies." (PMID 28615668, 2017).
Cognitive impairment (4 papers, 2019 to 2024). Abnormal cognition is characterized by deficits in thinking, reasoning, or remembering. "Grik1 accelerates cognitive impairment in mice, consistent with our sequencing results that Grik1 was highly expressed in InN1 and InN4, which were associated with the generation of cognitive impairment phenotype." (PMID 39635132, 2024). "Recent studies indicated that altered inhibitory transmission caused by GRIK1 [encoding GluR5 kainate receptor (KAR)] triplication was an important novel factor in cognitive deficits (e.g., memory impairment) in DS." (PMID 33329702, 2020). "We identified the triplication of a single gene, Grik1, as the cause of altered inhibitory transmission in the Ts2Cje mouse model of DS, defining its role in cognitive impairment." (PMID 31676751, 2019). "Our results suggest that a decrease in Grik1 may contribute to cognitive impairment." (PMID 39635132, 2024).
Alzheimer disease (3 papers, 2020 to 2025). A progressive, neurodegenerative disease characterized by loss of function and death of nerve cells in several areas of the brain leading to loss of cognitive function such as memory and language. "Both GRIK1 and UNC79 are involved in ion transmembrane transport and were not prioritised as likely causal genes in a recent GWAS of Alzheimer’s disease, highlighting the potential utility of FOCUS in gene prioritisation." (PMID 32299494, 2020).
autism (2 papers, 2017 to 2025). Persistent deficits in social interaction and communication and interaction as well as a markedly restricted repertoire of activity and interest as well as repetitive patterns of behavior. "The GRIK gene family (GRIK1, GRIK2, GRIK3, GRIK4, and GRIK5) has genetic variants that contribute to various illnesses, including Huntington's disease, Parkinson's disease, autism, and schizophrenia." (PMID 41327126, 2025).
behavioral disorders (2 papers, 2016 to 2025). "Accordingly, the behavioral disorders observed in our family suggest that GRIK1 might be considered the most favorable candidate gene." (PMID 27625702, 2016).
COVID-19 (2 papers, 2023 to 2025). A disease caused by infection with severe acute respiratory syndrome coronavirus 2. "By 6 weeks post-inclusion (T2), COVID-19 hypermethylation of genes with lowest p-value included NXN, FMNL2, ZBTB46, SLC35F3, and SHQ1, and the hypomethylated genes included ELMO1, XBP1, GRIK1, TNFAIP8, and SH3BP5." (PMID 41227320, 2025).
diabetes (2 papers, 2014 to 2025). "Having diabetes increases susceptibility to TB, and this may explain the GRIK1—GRIK3 interaction association we observed in the data." (PMID 25919455, 2014).
glioblastoma (2 papers, 2024). The most malignant astrocytic tumor (WHO grade IV). "To sum up, we identified seven genes (GRIA1, GRIA2, GRIK1, GRIK4, GRM3, GLUL, BCAT1) whose mRNA expression may serve as potential molecular biomarker candidates to distinguish glioblastoma and brain metastases tissue derived from surgical resections." (PMID 38835368, 2024).
hepatocellular carcinoma (2 papers, 2014 to 2024). A malignant tumor that arises from hepatocytes. "Meanwhile, polymorphisms in GRIK1 are associated with hepatitis B virus–related hepatocellular carcinoma (HCC) and coronary artery aneurysm (CAA) formation in patients with Kawasaki disease (KD)." (PMID 38560566, 2024).
ischemia (2 papers, 2014 to 2025). A hypoperfusion of the BLOOD through an organ or tissue caused by a PATHOLOGIC CONSTRICTION or obstruction of its BLOOD VESSELS, or an absence of BLOOD CIRCULATION. "Namely, the peptide reduced the expression of many genes (e.g., P2rx6, Gabra3, Grik4, Oprl1, Glra2, Crhr1, Hrh1, Chrm5, Grik1) related to the neurosignaling system and whose expression was not significantly changed by ischemia itself." (PMID 40650034, 2025).
Obesity (2 papers, 2017 to 2023). Accumulation of substantial excess body fat. "Interestingly, we found additional RSVs in patients in 4 of the selected genes (NPY, GRPR, SLCO4C1 and GRIK1) reinforcing their putative role in the pathophysiology of obesity." (PMID 28489853, 2017). "Among those, the genes encoding the neuropeptide Y (NPY), two glutamate receptors (GRIK1, GRM7), the X-linked gastrin-peptide receptor (GRPR), and the organic anion transporter (SLCO4C1) are novel obesity candidate genes that may contribute to highly penetrant forms of familial obesity." (PMID 28489853, 2017). "A total of 10 shared co-expressed partners were identified in the analysis between our 4 novel strongest candidate genes (GRIK1, GRM7, GRPR and SLCO4C1) and the set of 15 obesity-related genes described in the literature." (PMID 28489853, 2017). "To further assess the possible implication of these strong candidate genes (GRIK1, GRM7, GRPR and SLCO4C1), we determined the co-expression patterns between them and 15 well-defined genes from the leptin-melanocortin pathway previously related to obesity." (PMID 28489853, 2017).
attention deficit-hyperactivity disorder (1 paper, 2017). A disorder characterized by a marked pattern of inattention and/or hyperactivity-impulsivity that is inconsistent with developmental level and clearly interferes with functioning in at least two settings (e.g. at home and at school). "In addition to a gain of the NPY gene in a familial case with EOO and attention deficit hyperactivity disorder, likely pathogenic CNVs included gains of glutamate receptors (GRIK1, GRM7) and the X-linked gastrin-peptide receptor (GRPR), all inherited from obese parents." (PMID 28489853, 2017).
autism spectrum disorder (1 paper, 2025). A spectrum of developmental disorders that includes autism, and Asperger syndrome. "Interestingly, Genome-Wide Association Study on SNPs suggested that the glutamate receptor, ionotropic, kainate 1 (GRIK1) gene's rs363598 and intergenic rs360932 SNPs are correlated with autism spectrum disorder (ASD)." (PMID 41327126, 2025).
Hypertension (1 paper, 2024). The presence of chronic increased pressure in the systemic arterial system. "Among the glutamate receptors, the Grik1 gene stood out as being particularly downregulated in the CVLM during and after the onset of hypertension." (PMID 38145287, 2024).
seborrheic keratosis (1 paper, 2017). A common benign skin neoplasm usually affecting older individuals. "One seborrheic keratosis (SK14) carried a non-synonymous mutation in GRIK1 (c.1148C>A, p.G383D) and an intronic mutation in NEDD4 (c.3471-1C>T) with a potential effect on splicing (Human Splicing Finder)." (PMID 28410231, 2017).
Senile plaques (1 paper, 2011). Senile plaques are extracellular deposits of amyloid in the gray matter of the brain. "GRIA4 and GRIK1 are shown to be expressed in senile plaques (in temporal lobe) in microarray data but are not identified as expressed in the AD temporal lobe in the present RNA-Seq dataset." (PMID 21283692, 2011).
T-cell Lymphoma (1 paper, 2012). "Following the UCSC UMD3 assembly, candidate genes could be identified at or close to the peaks for regions #2 (TIAM1: T-cell Lymphoma Invasion and Metastasis 1), # 3 (GRIK1: Glutamate Receptor, Ionotropic, Kainate 1) and #4 (RAI14: Retinoic Acid Induced 14)." (PMID 22675421, 2012).
cancer (6 papers, 2012 to 2024). A tumor composed of atypical neoplastic, often pleomorphic cells that invade other tissues. "Our discovery of the association of GRIK1 with HCC has enhanced the emerging evidences for the important role of glutamate signaling pathway in cancer development." (PMID 22807686, 2012). "Regrettably, specific regulation mechanisms between GRIK1 involved in cancer invasive growth in GBM cells remain unclear, and transcriptional factors regulations after GRIK1 need further studies." (PMID 38560566, 2024). "We also observed somatic variants in several known cancer-associated genes (for example, JAG1, PRDM2, PRDM8, SETD2, ASPM, ZIC, GRIK1, etc.), which may be important for cell growth and proliferation." (PMID 30871634, 2019). "Finally, SNPs within GRIK1 have also been found significantly associated with paclitaxel response in NCI60 cancer cell lines, and may play a role in the cellular response to paclitaxel treatment in cancer." (PMID 22807686, 2012).
tumor (3 papers, 2017 to 2025). "Regarding GRIK1, the rs363599 G/G genotype is significantly associated with ∼35% less tumor burden after paclitaxel monotherapy [95% CI (–0.442, –0.267), p < 0.0001]." (PMID 29290962, 2017). "Interestingly, the larger effect on poor tumor response is in the GRIK1 gene (rs363599) as it is positively associated with × 1.33 greater tumor burden despite paclitaxel treatment (95% CI 0.39, 2.227, p = 0.047), followed by × 0.78 in LPHN2 (rs371363) (95% CI 0.24, 1.33, p = 0.005)." (PMID 29290962, 2017). "After adjusting for multiple clinical covariates, SNPs on the LPHN2, ROBO1, SNTG1, and GRIK1 genes were significant independent predictors of poor tumor response (tumor growth) despite paclitaxel treatment." (PMID 29290962, 2017). "Assuming a genotypic model of inheritance, genetic markers in the LPHN2 (also known as ADGRL2) and GRIK1 genes explained much of the variability in tumor response (14% and 10.4% respectively) in our data." (PMID 29290962, 2017). "This is the first report to have found a SNP of GRIK1 [rs363599] as a major independent suboptimal factor for tumor response to paclitaxel treatment." (PMID 29290962, 2017). "After adjusting for hormonal exposure and status, disease stage, and molecular subtype, in our sample, SNPs on the ADRGL2 ( p = 0.005), ROBO1 ( p = 0.047), SNTG1 ( p = 0.040), and GRIK1 ( p = 0.006) genes are significant independent predictors of tumor response to paclitaxel treatment." (PMID 29290962, 2017). "Additionally, CRC patients with low GRIK1 expression had shorter overall survival compared to those with high GRIK1 expression, further indicating that GRIK1 may function as a tumor metastasis suppressor in CRC." (PMID 40538623, 2025).
neurological diseases (2 papers, 2024). "Glutamate ionotropic receptor kainate type subunit 1 (GRIK1) is essential for brain function and is involved in many mental and neurological diseases." (PMID 38560566, 2024). "OMG, LRTM2, GRIK1, and CDH9 are predominantly expressed in the nervous system, participating in neuronal and synaptic functions, has a significant impact on the occurrence of various neurological disorders." (PMID 38979414, 2024).
adenocarcinoma (1 paper, 2013). A common cancer characterized by the presence of malignant glandular cells. "Multiple genes involved in olfactory transduction and neuroactive ligand-receptor interaction including OR13J1, OR51E2, GNAL, and GRIK1 were also found by this study to be mutated in the adenocarcinoma, suggesting these two classes of genes warrant further investigation." (PMID 23301059, 2013).
GRIK1 also shares sentences with these, for which no sentence is quoted: anxiety disorder (3 papers); Down syndrome (3); bipolar disorder (2); brain disorder (2); encephalitis (2); gastric cancer (2); glioma (2); juvenile absence epilepsy (2); migraine (2); psychiatric disorder (2); status epilepticus (2); temporal lobe epilepsy (2); Alcohol (1); amyloidosis (1); amyotrophic lateral sclerosis type 1 (1); cardiac arrhythmia (1); cocaine addiction (1); cognitive decline (1); colorectal adenoma (1); developmental delay (1); genetic generalized epilepsy (1); glioneuronal tumors (1); Guillain-Barre syndrome (1); Headache (1); Hodgkin’s disease (1); influenza (1); intellectual disabilities (1); liver cancer (1); medulloblastoma (1); memory impairment (1).
A further 9 diseases each share a sentence with GRIK1 in 1 paper.